RHOA (ras homolog family member A)
Diseases named in the same sentence as RHOA in open-access papers (continued):
Sharing a sentence is not in itself a finding about the gene and the disease.
heart failure (26 papers, 2005 to 2025). Inability of the heart to pump blood at an adequate rate to meet tissue metabolic requirements. "Cardiomyocyte-specific overexpression of RhoA or Rac1 causes cardiac failure in mice, and RhoGTPase signaling is activated in murine cardiomyopathy and human heart failure." (PMID 37926281, 2023). "In this context, we examined the cardiac RhoA expression in the heart samples obtained from adult patients with severe heart failure caused by idiopathic dilated cardiomyopathy (DCM)." (PMID 36758801, 2023). "It has been shown that RhoA plays some role in cardio-protective signaling, especially adaptive hypertrophy, but the detrimental effects of RhoA activation in cardiomyocytes predominate and it is associated with pathological hypertrophy and heart failure." (PMID 33906663, 2021). "Thus, we conclude that loss of RhoA in the heart induces heart failure due to early cardiac senescence and cardiomyopathy." (PMID 36758801, 2023). "Considering the clinical implication of Parkin expression supplementation in patients with heart failure caused by reduction or loss of RhoA, we additionally examined the effect of the Parkin gene transfer on RhoA cKO mice when cardiac function was mildly impaired." (PMID 36758801, 2023). "Also mice overexpressing RhoA are known to develop a lethal dilated cardiomyopathy associated with heart failure." (PMID 25821814, 2015). "On the other hand, RhoA is also essential for early heart development and has protective effects after cardiac injury, whereby RhoA promotes cardiomyocyte survival and delays the transition to heart failure." (PMID 40911671, 2025). "Recent evidence demonstrates that RhoA in cardiomyocytes prevents the development of heart failure induced by stress, such as pressure overload, ischemia and aging." (PMID 39122698, 2024). "This suggests that RhoA has cardioprotective effects and is crucial for the maintenance of healthy mitochondria, resulting in the prevention of heart failure with aging." (PMID 36758801, 2023). "RhoA signaling plays a pivotal role in processes leading to cardiovascular diseases, such as pulmonary hypertension, vasospastic angina, and heart failure." (PMID 36758801, 2023). "The heart was enlarged in RhoA cKO mice injected with control AAV-GFP due to heart failure, which was clearly recovered by AAV-Parkin-T2A-GFP injection." (PMID 36758801, 2023). "Further understanding of RhoA signaling in the aged heart will help to develop future therapies for the prevention and treatment of heart failure." (PMID 36758801, 2023). "Up-regulation of RhoA signaling and integrin signaling influences stress induced hypertrophy and is protective against heart failure; however, activation can also result in fibrosis." (PMID 37658118, 2023). "Collectively, these results indicate the severe low cardiac output condition and an accelerated transition to heart failure in RhoA cKO mice, resulting in a shorter lifespan." (PMID 36758801, 2023). "High levels of RGS3L, as found in heart failure, redirect the Gi-mediated Rac1 activation into a Gi-mediated RhoA/ROCK activation." (PMID 35230541, 2022). "RhoA is essential for cardiac remodeling, and its cardiac-specific overexpression results in dilated cardiomyopathy and heart failure." (PMID 35621843, 2022). "Overexpression of Ras homolog family member A (RhoA), a GTPase of the Rho subfamily, stimulates heart failure and mitochondrial apoptosis due to increased Bax." (PMID 36036015, 2022). "Experiments with mouse models and pressure overload-induced hypertrophy indicate that RhoA is necessary to prolong the transition from adaptive to maladaptive hypertrophy with dilation or heart failure." (PMID 33906663, 2021). "Taken together the results suggest that RhoA/ROCK1 pathways play a main role in the severe state of hypertrophy, which is associated with dilation, fibrosis and heart failure." (PMID 33906663, 2021).
heart failure (continued). "As early as in 1999, it was shown that mice overexpressing RhoA (~ 20-fold) from early development in a cardiac-specific manner develop dilated cardiomyopathy with heart failure and die within a few weeks of age." (PMID 33906663, 2021). "RhoA in cardiomyocytes can have both detrimental and beneficial effects on the heart as it has been reported to prevent progression of dilation and heart failure, but also promote the cardiac fibrosis." (PMID 31948008, 2020). "During heart failure, thrombin activates the RhoA signaling to stimulate its extravasation through the endocardium and to induce remodeling of atrial myocardium (Visual Abstract)." (PMID 27642643, 2016). "Increased RhoA/ROCK signaling can potentially contribute to heart failure." (PMID 39199201, 2024). "The RhoA/ROCK pathway contributes to the pathogenesis of heart failure, due to oxidative stress." (PMID 39199201, 2024). "There is no definitive knowledge about the RhoA expression in aged patients who suffer from heart failure without known hereditary gene mutations." (PMID 36758801, 2023). "Similarly, the lung weight, which was also increased by heart failure-induced pulmonary edema in RhoA cKO mice, was reduced by AAV-Parkin-T2A-GFP injection." (PMID 36758801, 2023). "Furthermore, the RhoA-knockout diminished the TAC-induced fibrosis and apoptosis associated with the severe stage of heart failure." (PMID 33906663, 2021). "Moreover, they also show a cardio-protective role of RhoA by (extending) compensatory hypertrophy and prolonging the transition to pathological hypertrophy, i.e. fibrosis and heart failure." (PMID 33906663, 2021). "In vivo, however, cardiac-specific overexpression of RhoA leads to development of heart failure." (PMID 30965672, 2019). "Mice overexpressing RhoA develop a lethal, dilated cardiomyopathy and heart failure." (PMID 25821814, 2015). "Mice overexpressing either wild type RHOA or an activated form of RHOA under the control of the cardiac-specific αMhc promoter died prematurely and developed cardiac enlargement, cellular hypertrophy, interstitial fibrosis, and heart failure." (PMID 22934047, 2012). "Especially in fibroblasts, RhoA induces proliferation and migration, which could account for example for the effects regarding fibrosis and thus the promotion of transition from adaptive to pathological hypertrophy with heart failure." (PMID 33906663, 2021). "Similarly, chronic inhibition of the RhoA/ROCK pathway may prevent adverse remodeling in experimental heart failure models, but its physiological role in regulating contractility remains unclear." (PMID 24919197, 2014). "The cardioprotective mechanism of QSKL on heart failure is probably mediated by regulating both the MAPK and RhoA signaling pathways." (PMID 28484504, 2017). "Absence of RhoA in the heart did not affect the TAC-induced upregulation of the fetal genes NppB and MYH7, which are generally associated with hypertrophy and heart failure." (PMID 33906663, 2021). "In vitro, leptin induces cardiomyocyte hypertrophy involving MAPK and RhoA-GTP, which contribute to morphological and phenotypic changes in cardiac size, structure, function, and heart failure." (PMID 23924318, 2013).
liver fibrosis (25 papers, 2015 to 2025). "In conclusion, the NOX4/ROS and RhoA/ROCK1 signalling pathways are closely linked to the development of liver fibrosis." (PMID 32496208, 2020). "The expression of liver fibrosis-associated factors also decreased in UA-treated liver fibrotic mice following RhoA inhibition." (PMID 32496208, 2020). "In liver fibrosis mice with RhoA inhibition via injection of adeno-associated virus, the liver fibrosis, intestinal damage, and flora disturbances were improved." (PMID 31736766, 2019). "In addition, analysis of the composition of the flora at the level of the phylum and genus also suggested the decline in Firmicutes and Lactobacillus caused by liver fibrosis has partially restore in the liver fibrosis mice with NOX4 or RhoA intervention." (PMID 32083022, 2020). "We examined the ileal RhoA signaling pathway in liver fibrosis mice and the changes caused by UA." (PMID 31736766, 2019). "AKT/RhoA inhibitors reduced progressive liver fibrosis, providing a potential therapeutic strategy for MAFLD treatment." (PMID 36918564, 2023). "RhoA had also been found to be involved in the pathological processes of liver fibrosis and silicosis fibrosis." (PMID 37864185, 2023). "Previous studies have shown that miR-125b can promote hepatic stellate cell activation and liver fibrosis by activating RhoA signaling, and antagonizing miR-125b can significantly alleviate liver fibrosis in CCl4-treated mice." (PMID 36359344, 2022). "BMSC and FA treatment attenuated HSC activation and liver fibrosis by inhibiting cytoskeletal rearrangement and delivering miR-19b-3p to activated HSCs, inactivating RhoA/ROCK signalling." (PMID 35721175, 2022). "miR-125b-5p has been reported to suppress liver fibrosis in non-alcoholic fatty liver disease by inhibiting the RhoA signaling pathway." (PMID 34344478, 2021). "This function is realised through the RhoA/Rho-kinase pathway, which also promotes liver fibrosis and portal hypertension by activating hepatic stellate cells." (PMID 32868783, 2020). "The results of dual immunofluorescence and the expression of liver fibrosis-related factors also show the importance of RhoA in liver fibrosis." (PMID 32496208, 2020). "To demonstrate the role of RhoA in liver fibrosis in vivo, we constructed liver fibrotic mice in which RhoA was inhibited with AAV viruses or inhibitors." (PMID 32496208, 2020). "Both NOX4 and RhoA are profibrotic factors that play an important role in liver fibrosis, and they have a close interaction in fibrotic diseases." (PMID 32083022, 2020). "In summary, we identified TGF-β1-induced activation of PYK2-Src-RhoA triad leads to YAP/TAZ activation for CTGF induction in liver fibrosis." (PMID 33273492, 2020). "We identified that TGF-β1-induced activation of PYK2-Src-RhoA triad leads to YAP/TAZ activation for CTGF induction in liver fibrosis." (PMID 33273492, 2020). "Compared to that in the CCl4 group, the mRNA level of NOX4 in the RhoAi group was decreased to a certain degree, but this difference was not statistically significant, indicating that NOX4/ROS is the upstream signalling pathway of RhoA/ROCK1 in liver fibrosis." (PMID 32496208, 2020). "Correspondingly, the hydroxyproline content was lower in RhoA-inhibited mice with liver fibrosis than in control mice." (PMID 32496208, 2020). "In the NOX4 intervention and RhoA intervention groups, related experimental analyses confirmed the decrease in CCl4-induced liver fibrosis." (PMID 32496208, 2020). "We also demonstrated in vitro that after induction of RhoA activation in HSCs, cellular proliferation and migration and the degree of cytoskeletal F-actin polymerization increased, and the expression of liver fibrosis-related factors also increased." (PMID 32496208, 2020). "The results showed that in the liver fibrosis mice treated with NOX4 or RhoA, the disordered intestinal microbiota showed different degrees of improvement." (PMID 32083022, 2020).
liver fibrosis (continued). "In liver fibrotic mice in which NOX4 and RhoA were inhibited, the effect of UA in improving liver fibrosis declined to a certain degree, and the expression of liver fibrosis-related factors was also altered." (PMID 32496208, 2020). "Our study further verified the effect of carvedilol on the AT1R-mediated RhoA/ROCK2 pathway in mice with CCl4-induced liver fibrosis." (PMID 31828132, 2019). "In our study, we found that in RhoA-inhibited liver fibrosis mice, bacterial disorder was partly rescued." (PMID 31736766, 2019). "In conclusion, our research indicates that UA improves intestinal integrity and bacteria through RhoA-related signaling pathways, which provides strong evidence that UA indirectly contributes to the improvement of liver fibrosis through the gut–liver axis." (PMID 31736766, 2019). "The present study investigated the interaction between NOX4/ROS and RhoA/ROCK1 in hepatic fibrosis, the direct binding of NOX4 and RhoA, and the specific antifibrosis molecular targets of UA." (PMID 31130857, 2019). "Recent studies have found that RhoA participates in the regulation of hepatic fibrosis by regulating the migration, adhesion, contraction, proliferation, and apoptosis of HSCs." (PMID 31130857, 2019). "The RhoA/Rho-kinase pathway is one of the pathways that participate in the development of hepatic fibrosis and portal hypertension." (PMID 31828132, 2019). "RhoA expression was significantly elevated in human and experimental liver fibrosis, while c-SRC was inactivated." (PMID 26696895, 2015). "In liver fibrosis, upregulation of the RhoA/ROCK axis leads to increased vascular contractility and portal pressure." (PMID 26696895, 2015). "Our group has demonstrated several times that the signaling cascade via JAK2, RhoA, and Rho-kinase signaling is upregulated in liver fibrosis and located mainly in myofibroblast-like activated HSC." (PMID 26696895, 2015). "Note, under hypoxic conditions and through upregulation of the transcription factor PPARγ, miRNA-27b plays an essential role in lipid metabolism while silencing of miRNA-125b-5p promotes liver fibrosis in MASLD via integrin α8-mediated activation of the RhoA signaling pathway." (PMID 39424772, 2025). "We found that FA could promote the ability of BMSCs to reduce liver fibrosis via the RhoA/ROCK pathway." (PMID 35721175, 2022). "In the present study, we aim to explore how Echinococcus multilocularis soluble antigen induces macrophage polarization following alveolar echinococcosis infection, thus activating hepatic stellate cells and inducing liver fibrosis through the RhoA-MAPK signaling pathway." (PMID 35324411, 2022). "Therefore, Echinococcus multilocularis soluble antigen remarkably activated the RhoA-MAPK pathways in macrophages, further inducing the polarization of macrophages and ultimately causing liver fibrosis." (PMID 35324411, 2022). "We investigated the interaction between NOX4/ROS and RhoA/ROCK1 during liver fibrosis and whether these molecules are targets for the anti-fibrotic effects of UA." (PMID 32496208, 2020). "We aimed to determine the relationship between NOX4/ROS and RhoA/ROCK1 in liver fibrosis." (PMID 32496208, 2020). "Studies have shown that RhoA and its downstream signaling molecules are expressed in hepatic vascular smooth muscle cells, vascular endothelial cells, and HSCs, increasing hepatic vascular resistance and aggravating hepatic fibrosis." (PMID 31130857, 2019). "Thus, RhoA participates in the regulation of hepatic fibrosis by regulating the activation, migration, adhesion, contraction, and proliferation of HSCs." (PMID 31130857, 2019). "Studies have shown that RhoA and its downstream signaling molecules are expressed in hepatic vascular smooth muscle cells, vascular endothelial cells, and HSCs, increasing hepatic vascular resistance and aggravating liver fibrosis." (PMID 31130857, 2019).
liver fibrosis (continued). "Furthermore, in RhoA-inhibited liver fibrosis mice, the destruction of the intestinal barrier integrity was also decreased (P < 0.05)." (PMID 31736766, 2019). "However, little is known about the role of c-SRC and the interplay with RhoA in liver fibrosis in general and in activated HSCs in particular." (PMID 26696895, 2015). "Our ex vivo experimental data suggest that elevated interstitial fluid hydrostatic pressure under pathological conditions may promote liver fibrosis by inducing acquisition of profibrotic properties of hepatic stellate cells through the RhoA/ROCK signaling pathway." (PMID 35357779, 2022). "In this study we demonstrated that elevated fluid hydrostatic pressure under pathological conditions may subsequently promote liver fibrosis by activating hepatic stellate cells through the RhoA/ROCK signaling pathway, providing a possible target for preventing fibrosis progression." (PMID 35357779, 2022). "We assessed whether UA reverses liver fibrosis by inhibiting RhoA-related signalling pathways." (PMID 32496208, 2020). "This suggests that NOX4/ROS may be the upstream signalling pathway of RhoA/ROCK1 in liver fibrosis." (PMID 32496208, 2020). "RhoA and its downstream signaling molecules can be expressed on the surface of hepatic vascular smooth muscle cells, vascular endothelial cells and HSCs, which can aggravate liver fibrosis by regulating HSC activation, migration, adhesion, contraction, proliferation, and apoptosis." (PMID 32083022, 2020). "However, it is unknown whether UA directly affects the intestinal microbiota by inhibiting NOX4 and RhoA or indirectly improves the intestinal microbiota by reducing liver fibrosis." (PMID 32496208, 2020). "Besides increased matrix stiffness, which is only one factor of liver fibrosis, the crosstalk of RhoA, and c-SRC may be triggered by other factors such as proinflammatory or profibrotic cytokines upon liver disease progression." (PMID 26696895, 2015). "Regarding liver fibrosis, CB1 promotes M1 macrophage polarization in mice through two independent pathways, RhoA/NF-κB and ERK1/2, leading to liver fibrosis." (PMID 38397045, 2024). "RhoA and AKT inhibitors are currently only in Phase 3 trials or preclinical studies for the treatment of liver fibrosis or clinical tumors, with therapeutic potential for MAFLD64–66." (PMID 36918564, 2023). "Profibrotic factors NOX4 and RhoA participate in the activation of HSC and accelerate the development of liver fibrosis." (PMID 32083022, 2020). "We have demonstrated that Rac1 is involved in NOX activation and that NOX4/ROS can also induce HSC activation by activating the RhoA/ROCK1 signaling pathway, thereby promoting liver fibrosis." (PMID 32083022, 2020). "To examine the effects of RhoA on liver fibrosis in vivo, we constructed RhoA-inhibited liver fibrotic mice by injecting the mice with AAV and the RhoA inhibitor fasudil." (PMID 32496208, 2020). "UA treatment significantly decreased the induced ileal expression level of RhoA and ROCK in liver fibrosis mice (P < 0.01)." (PMID 31736766, 2019). "In conclusion, these results suggest that FA combined with BMSC treatment can induce greater release of miR-19b-3p, which inhibits the activation of HSCs by suppressing the RhoA/ROCK1/SRF and RhoA/ROCK1/LIMK1 pathways, contributing to alleviation of liver fibrosis." (PMID 35721175, 2022). "Hypothesis: We hypothesize that infection with Echinococcus multilocularis activates the RhoA-MAPK signaling pathway and subsequently induces macrophage polarization to promote hepatic stellate cells activation leading to liver fibrosis." (PMID 35324411, 2022). "We explored the underlying mechanisms involved in this effect and found that the UA-induced reversal of liver fibrosis may be achieved by inhibiting the NOX4/ROS and RhoA/ROCK signalling pathways, which may interact with each other." (PMID 32496208, 2020).